MIF (macrophage migration inhibitory factor)
Diseases named in the same sentence as MIF in open-access papers (continued):
Sharing a sentence is not in itself a finding about the gene and the disease.
tumor (continued). "Several cytokines are known to be involved in tumor development and immune modulation, including tumor necrosis factor (TNF)-α, IL-6, IL-10, IL-12, IL-17, transforming growth factor (TGF)-β, and macrophage migration inhibitory factor (MIF)." (PMID 41051525, 2025). "ST data further confirmed the spatial co-localization of tumor and immune cells, as well as the expression of co-inhibitory ligand–receptor pairs, such as SPP1/CD44 and MIF/CD74, highlighting the mechanism by which tumor cells promote immune escape through the expression of co-inhibitory factors." (PMID 40867511, 2025). "In addition to tumor cells secreting MIF cytokines to regulate immune cells, other stromal cells in HCC also influence the immune microenvironment through the MIF signaling pathway." (PMID 40018995, 2025). "On dividing cells into SSR4-positive and -negative groups, CellChat analysis indicated that SSR4 may regulate the interactions that existed between ESCC tumor plasma cells and the tumor microenvironment (TME) by modulating the MIF/CD74/CXCR4 axis." (PMID 40066443, 2025). "In TP53Q/Q cohorts, the total tumor numbers per mouse had not changed 5 weeks after TAM-induced MIF ablation." (PMID 40835826, 2025). "Blocking IL-6 or IL-6R did not decrease viability nor migration of the cancer cells, whereas inhibiting macrophage migration inhibitory factor (MIF) did decrease tumor cell migration, but not viability." (PMID 40061210, 2025). "Furthermore, we found that, compared to tumor tissues, T cell subsets in normal tissues were more regulated by iCAFs and apCAFs through pathways such as CXCL12-CXCR4 and MIF-(CD74+CXCR4)." (PMID 40740774, 2025). "Across both tumor clusters, MDK–(ITGA4+ITGB1) and MIF–(CD74+CXCR4) emerged as prominent axes." (PMID 40948762, 2025). "Therefore, MIF acts as a major mediator amplifying HPV-driven oncogenic signaling and tumor microenvironment remodeling." (PMID 41472252, 2025). "Additionally, MIF signaling through the CD74/CD44 receptor complex activates the ERK MAP kinase pathway, further promoting tumor cell proliferation." (PMID 41159021, 2025). "The interaction between the BM microenvironment and NB cells is mediated, in part, by the MIF/CXCR4 signaling axis irrespective of the tumor cell biology." (PMID 38730688, 2024). "Specifically, CD36+ CAFs could import oxidized lipids, which stimulated the production of macrophage migration inhibitory factor (MIF), a molecule responsible for tumor accumulation of myeloid-derived suppressor cells." (PMID 38338736, 2024). "Specifically, MIF can activate downstream signaling pathways such as MAPK (Mitogen-Activated Protein Kinase) and PI3K (Phosphoinositide 3-Kinase) by binding to CD74, promoting tumor cell proliferation, survival, and metastasis." (PMID 38277205, 2024). "We now know that MIF is expressed by immune, stromal, and tumor cells, and binds to three known non-cognate receptors in addition to CD74, with implications in normal and aberrant immune responses." (PMID 38730725, 2024). "This was not examined across a 24 h period, and time-of-day information is not reported; therefore, it is possible that tumor-derived MIF expression is also circadian." (PMID 38730725, 2024). "Summarily, CD8, CD68, CD206, MIF, and CXCR4 expression are related with tumor progression." (PMID 39464891, 2024). "The differential presence or absence of the MIF-related pathway between FABP6+ tumor cells and normal tissues highlights a potential role of MIF signaling in the tumorigenic processes associated with FABP6+ tumor cells." (PMID 38277205, 2024). "Tumor tissue micro vessel density (MVD) was significantly lower and pericyte coverage was significantly increased in both the whole-brain irradiation group and MIF-silenced group compared with the control group." (PMID 38685050, 2024). "The PLOD2 + SAA1 + tumor cells could communicate with other cells through ligand-receptor pairs like SPP1-CD44, MIF-(CD74 + CXCR4), and MDK-LRP1." (PMID 38951896, 2024).
tumor (continued). "Further, we found that blocking MIF/CD74 axis in vivo could improve the efficacy of radiotherapy and exert anti-tumor effects by inducing microglia polarization toward M1 type after radiotherapy." (PMID 38685050, 2024). "Treatment with rSmeg-hMIF-hIL-7, a vaccine which could induce anti-MIF immune response, enhanced activation of CD4 + and CD8 + T cells in a MC38 tumor-bearing mouse model." (PMID 38685050, 2024). "The MIF/CXCR4 axis is the most ligand–receptor interaction between macrophages and tumor cells." (PMID 39464891, 2024). "Furthermore, the iso-ligand receptors MIF-(CD74+CXCR4) and MIF-(CD74+CD44) regulate T/NK cells, potentially facilitating tumor cell evasion of immune surveillance." (PMID 39712016, 2024). "Furthermore, the MIF/ACKR3 axis is critical in various biological processes, including lymphocyte chemotaxis and tumor cell proliferation." (PMID 39896809, 2024). "The L–Rs including the MIF-(CD74+CXCR4) and collagen/fibronectin/laminin-CD44 interactions in MTs may create a tumor immunosuppressive microenvironment." (PMID 38414027, 2024). "Taken together, TAM‐derived MIF may promote CD74 activation, thus facilitating the PI3K‐STAT3‐PD‐L1 signalling pathway, ultimately resulting in immune escape and tumour progression." (PMID 39113235, 2024). "Additionally, MIF induces differentiation of myeloid-derived suppressor cells (MDSCs) within the TME, further enhancing tumor permissiveness and immune evasion." (PMID 38732068, 2024). "Moreover, MIF-(CD74 + CD44) signaling between fibroblasts and cholangiocytes, dendritic cells and T cells was significantly enhanced in tumor tissue." (PMID 38702814, 2024). "MIF can be secreted as an immunosuppressive factor in the tumor microenvironment, and blocking CD74/MIF signaling enhances CD8+ T cell infiltration and drives macrophage pro-inflammatory conversions and anti-tumor function." (PMID 38730725, 2024). "In addition, proinflammatory cytokines such as IL‐8, MIF, TNF‐ α, and so on, were significantly upregulated in tumor tissues." (PMID 38041547, 2024). "Additionally, our study identified the tumor cell subgroup Str1, characterized by MME+ (gene of CD10 protein) expression, through a combination of H&E and miF staining." (PMID 39676856, 2024). "MIF is known for its involvement in immune response and inflammation regulation, and its impact on the TME may influence tumour immune escape and progression." (PMID 39031800, 2024). "MET, GPI, ANGPTL4, HSPA5, TGFA, MIF, and ARTN were significantly up-regulated in tumor samples." (PMID 36447119, 2023). "Mechanistically, MIF independently interacts with CD74 in a hetero-complex with CD44, CXCR2, CXCR4, and ACKR3 to initiate downstream MAPK and PI3K pathways, all of which influence tumor initiation, growth, and metastatic dissemination." (PMID 38065972, 2023). "Intercellular interaction analysis suggested that MFAP5 + fibroblasts could reciprocally communicate with C1QC + macrophages and other myeloid cells to remodel unfavorable conditions via MIF/CD74, IL34/CSF1R, and other tumor-promoting signaling pathways." (PMID 37344903, 2023). "Taken together, these analyses suggest that, while the rs755622 MIF SNP did not associate with differences in GBM incidence or survival, rs755622 did correlate with a difference in the immune cell composition of the tumor microenvironment." (PMID 37252795, 2023). "Briefly, the tumor (N = 7) and adjacent (N = 6) tissues of OS patients were collected and stained using IHC, showing that CSNK2A2, VDAC2, and MIF were markedly upregulated in OS tissues compared with the control tissues, whereas the expression of ODC1 showed no significant change." (PMID 37231440, 2023). "MIF-activated CD44 is expressed in cells with dynamic proliferation, such as tumor cells." (PMID 37240298, 2023).
tumor (continued). "Nevertheless, there is more and more evidence from in vitro research and preclinical murine tumor models that the targeting of both MIF and DDT could have superior anti-tumor effects." (PMID 36672343, 2023). "MIF is known to be involved in modulating immune responses and inflammation, and its involvement in the TME may have far-reaching implications for tumor immune evasion and progression." (PMID 37671160, 2023). "Recent work from our laboratory and others has shown that MDSCs are increased in the circulation and tumor microenvironment, they portend a poor prognosis, their expansion can be driven by CSC-derived MIF, and they can be reduced by MIF neutralization (either genetically or pharmacologically)." (PMID 37252795, 2023). "In addition, we noted that Scissor+ tumor cells downregulated MHC I and MHC II signaling and upregulated inflammatory MIF signaling‐mediated cellular interactions." (PMID 37021816, 2023). "Among them CCNB1, MIF, PLA2G4A may be regarded as oncogenes, whereas RNASE3, APOE, FOXO1, KIT, and EGR1 may be tumor suppressor genes." (PMID 37065484, 2023). "Next, the results of cell-cell communication analysis suggested that pericytes interact with broad immune cells via MDK-NCL pathways in metastasis samples, MIF-(CD74+CXCR4) and MIF-(CD74+CC44) interaction especially occurred between different cell types in tumor and normal samples." (PMID 37335089, 2023). "On one hand, these microparticles recruit monocytes producing IFN-γ and IL-4, which are involved in the tumoricidal function of macrophages, via the chemoattractants RANTES/CCL5, MIF (macrophage migration inhibitory factor), CCL2 and CXCL12; thus, they suppress primary tumor growth." (PMID 36831450, 2023). "Our findings indicate that tumor cells with high m7G scores exert significant autocrine and paracrine effects on the cellular communication network through multiple tumor growth-promoting signals (FGF5 and SEMA3C) and immunosuppressive signals (MIF and TGF-β)." (PMID 37868988, 2023). "Several proteins that are involved in tumor vascularization were detected: histidine-rich glycoprotein (HRG), α-2-HS-glycoprotein, leucine-rich α-2-glycoprotein (LRG), secreted GRP78, macrophage migration inhibitory factor (MIF), VEGFA, and hepatoma-derived growth factor." (PMID 35659255, 2022). "One investigation may provide some indirect clues and found that macrophage migration inhibitory factor (MIF) is highly expressed in GBM tumors and enhances tumor cell autophagy and migration by activating ROCK1." (PMID 35920986, 2022). "Similarly, overexpressed MIF in PC cells enhances ZEB1/2 and reduces miR-200b expression, in turn, inducing EMT, tumor growth and metastasis in vivo." (PMID 35842634, 2022). "Fifty-seven PDAC patients showing negative or weak tumour MIF expression had a better OS (P = 0.007) and a trend for increased PFS (P = 0.08) compared with the 27 patients whose tumour showed strong MIF expression using Kaplan−Meier analyses." (PMID 36703790, 2022). "It is not difficult to find that TA-MSCs, TA-MSCs-EVs and MIF show a certain degree of similarity in the mechanism of inhibiting tumor cell apoptosis, which is reflected in the coincidence of signaling pathway, tumor type and apoptosis-related proteins." (PMID 35842634, 2022). "We found strong interactions between tumor cells and TAM populations mediated by macrophage migration inhibitory factor (MIF) and its receptors (CD44 and CD74), which have been well characterized to play vital roles in tumor progression, angiogenesis, and immune escape in ccRCC70–72." (PMID 35853872, 2022). "Notably, in castration-resistant PCa patient specimens, both the macrophage migration inhibitory factor (MIF) and CXCR7 are overexpressed, and their subsequent blockade inhibits castration-resistant PCa tumor growth and potentially prevents metastasis." (PMID 35406450, 2022).
tumor (continued). "TA-MSCs, TA-MSCs-EVs and MIF show similar inhibitory effects on DCs, they can inhibit DCs recruitment into immunosuppressive TME, meanwhile suppress maturation and activation of DCs, thus indirectly promoting tumor progression." (PMID 35842634, 2022). "Expression profiles of MIF, CXCL12, and the receptors CXCR4, CXCR2, CXCR7, CD74, and CD44 were first analyzed using an RNA sequencing (RNA-seq) dataset (GSE62564) of 498 primary NB tumor samples." (PMID 35715791, 2022). "A further study suggests that MIF relies on its tautomerase activity to promote myeloid cell differentiation into mononuclear MDSCs (mMDSCs), promoting the formation of immunosuppressed TME and consequently, tumor growth and metastasis." (PMID 35842634, 2022). "Finally, we demonstrated that TAMs directly regulated tumor cells through GRN and MIF signaling pathways, while regulated themselves through inhibition of CCL and GALECTIN signaling pathways during the invasion process." (PMID 35523772, 2022). "In contrast, other pathways prominently change their information flow at PBMC or normal as compared to tumor tissue: (i) turn off (BAG), (ii) decrease (such as BAFF, FLT3, and IL1), (iii) turn on (such as GAS and LIGHT), or (iv) increase (such as MIF, PARs, ANNEXIN, and IL16)." (PMID 35812372, 2022). "Specifically, multiple signaling pathways may be activated in the tumor microenvironment of subtype A, including TNF, SPP1, MIF, ANGPL, and ANGPTL." (PMID 36199581, 2022). "TNFα produces and maintains a network of other mediators that promote tumor growth and peritoneal spread by stimulating the release of IL-6 and other chemokines such as CCL2 and CXCL12, macrophage migration-inhibitory factor (MIF), and VEGF." (PMID 36142615, 2022). "Furthermore, macrophage migration inhibitory factor (MIF) correlates with decreased GAD migration as well as decreased maturation, likely contributing to the tumor-tolerant immune state observed in GBM." (PMID 35711434, 2022). "Numerous studies demonstrated that MIF has been involved in the migration and invasion of cancer cells by up-regulating the pro-metastatic mediators MMPs, among which MMP2 and MMP9 degrades the ECM and facilitates the tumor cell invasion and metastasis." (PMID 36703790, 2022). "Macrophage migration inhibitory factor (MIF) signaling network, as the strongest signal from CSCs, which was mutually interacted by different LR pairs, mediated the cell-cell interaction between tumor cells and immune cells." (PMID 36451812, 2022). "Besides, the expressions of CXCL12-CXCR4, EGFR-MIF, FGFR1-FGR7, MIF-TNFRSF14, and WNT5A-PTPRK were predicted in the cross-talk between CAFs and tumor cells." (PMID 35784460, 2022). "MIF is highly expressed in head-and-neck cancer (HNC) and stimulates functions of neutrophils by enhancing their CXCR2-dependent recruitment and survival and release of CCL4 and MMP9, in turn, promoting tumor progression." (PMID 35842634, 2022). "Six pathways were specifically active in tumors compared to PBMC, including known inflammatory signals MIF, TNF, and IL16, suggesting that these pathways might critically contribute to tumor progression." (PMID 35812372, 2022). "In conclusion, our study revealed the expression pattern of tRFs in both tissue and plasma exosomes and identified a novel tRF, tRF-3022b, which may affect CRC tumor growth and M2 macrophage polarization by binding to LGALS1 and MIF." (PMID 36527118, 2022). "MIF also triggers TAMs polarization into M2 tumor-promoting phenotypes via CD74 and CXCR7 signal transduction, which not only increases the pro-angiogenic potential of TAMs but also promotes MM cell survival, proliferation, tumor growth and metastasis." (PMID 35842634, 2022). "Analysis of MIF in serum samples was able to distinguish metastatic tumours from those without metastases, as well as tumours in the P1–2 stage from those in the P3 stage with a 95.7% discriminatory sensitivity." (PMID 36167539, 2022).
tumor (continued). "Finally, we identified that TAMs regulated tumor cells through GRN and MIF signaling pathways, while TAMs self-regulated through inhibition of CCL and GALECTIN signaling pathways during the invasion process." (PMID 35523772, 2022). "For example, macrophage migration inhibitory factor (MIF) is an immunomodulator that can be induced by pituitary hormones, enhancing the production of inflammatory cytokines such as TNF, IL-1, and IFN, to play its role of anti-tumor or tumor promotion." (PMID 34090476, 2021). "Additionally, miRNA-451, which inhibits the macrophage migration inhibitory factor (MIF) and functions as a tumor suppressor, is also downregulated after H. pylori infection in GC cells." (PMID 34439541, 2021). "MIF immunoreactivity was moderately observed in both epithelial and non-epithelial areas, strongly observed in tumor nests, and moderately observed in tumor stroma." (PMID 34407796, 2021). "In our study, we investigated whether MIF promotes tumor growth in an autochthonous colorectal azoxymethane (AOM)/dextran sodium sulfate (DSS) mouse model and whether MIF can serve as a potential drug target." (PMID 33542244, 2021). "In addition, this paper also briefly describes the mechanism of action of the other three adipokines, resistin, MIF and MCP-1 in tumor and their therapeutic strategies." (PMID 34485124, 2021). "Accordingly, we supposed that MIF and SOX-4 factors may cooperate in acquiring invasive properties by tumor cells in prostate malignancies." (PMID 34157052, 2021). "Altered subcellular expression of MIF, SOX-4, β-catenin and E-cadherin may significantly contribute to tumor aggressiveness." (PMID 34157052, 2021). "MIF also affected tumor cell proliferation in AOM/DSS-induced tumors, which might explain the smaller tumors observed in Mif−/− mice." (PMID 33542244, 2021). "Notably, MIF has been reported to be overexpressed in several cancers, and the interaction between MIF and CD74 has also been shown to promote cell proliferation and tumor growth." (PMID 34805184, 2021). "Moreover, intracellular MIF binds to JAB1 and results in tumor cell cycle progression and proliferation." (PMID 33776775, 2021). "MIF is upregulated in human tumors and promotes tumor growth, which is independent of its tautomerase activity." (PMID 34012010, 2021). "As for humoral factors, VEGF, macrophage migration inhibitory factor (MIF), IL-6, IL-4/13, IL-10, TGFβ, POSTN, colony-stimulating factor-1 (CSF-1), CCL2, CXCL12, and COX-2/PGE2 directly or indirectly regulate the immunosuppressive tumor microenvironment." (PMID 32707672, 2020). "In seeking to target the interaction of MIF and CD74 on MDSCs we identified Ibudilast as an agent of interest, and were able to treat mice to reduce CD74 expression and increase CD8 T cells in the tumor." (PMID 32625208, 2020). "IL8, MIF, and CXCL8 lead to neutrophils infiltration at the tumor site." (PMID 33374253, 2020). "A growing body of evidence suggests that MIF and probably DDT could be involved in tumorigenesis by inhibiting antigen presentation and cytotoxic immune responses and favoring tumor evasion from immune recognition." (PMID 32155795, 2020). "Before RT, the only protein expressed in the tumor-free lung of the RP-G1 patient was ICAM while the tumor-free lung of the RP-G3 patient presented an overexpression of CD154, CXCL-1, ICAM, IFN-γ, IL-1ra, IL-23, MIF and PAI-1." (PMID 33109238, 2020). "Whether MIF-dependent CCL4 expression in TANs has pro- or anti-tumorigenic effects likely depends on which immune cells infiltrate and how the tumor microenvironment specifically activates these cells." (PMID 33324425, 2020).